PLIN1 (perilipin 1)
Diseases named in the same sentence as PLIN1 in open-access papers (continued):
Sharing a sentence is not in itself a finding about the gene and the disease.
breast carcinoma (29 papers, 2015 to 2025). "More recently it has been demonstrated that PLIN1 expression is downregulated in breast cancer, and that reduced expression of PLIN1 in ER+ and luminal A subtypes is associated with a poor prognosis and decreased any event-free overall survival." (PMID 28412757, 2017). "The MR (p = 0.0003, HR = 0.89, 95% CI = 0.84–0.95) and AE (p = 0.0006, HR = 0.92, 95% CI = 0.87–0.96) data indicated that low PLIN1 expression is associated with poor prognosis for breast cancer." (PMID 27359054, 2016). "In breast cancer, lipid droplet formation is reported to be associated with prolonged breast cancer survival, so this could explain our result of PLIN1 positivity and its association with poor prognosis." (PMID 26334757, 2015). "In breast cancer, the high expression of PLIN1 correlated with a good prognosis, but PLIN2 and PLIN4 expression correlated with a poor prognosis." (PMID 37998612, 2023). "The presence of lipid droplet-containing adipocytes as well as breast cancer cells in co-spheroids was confirmed by co-staining of perilipin-1 (adipocytes) and pan-cytokeratin (tumor cells)." (PMID 37444610, 2023). "For PLIN1, the study found that its mRNA expression is significantly downregulated in human breast cancer." (PMID 37609286, 2023). "By using GSE65194, we performed ROC curve analysis to access the diagnostic value of four DEmRNAs (TFF1, COL10A1, LEP, and PLIN1) and two DEmRNAs (PGM5-AS1 and TRHDE-AD1) in luminal A breast cancer." (PMID 35692369, 2022). "PLIN1 is markedly declined in human breast cancer, and overexpression of PLIN1 in human breast cancer cells dramatically suppresses cell proliferation, invasion, and in vivo tumorigenesis." (PMID 35692369, 2022). "The downregulation of PLIN1 mRNA has been reported in breast cancer and is considered a tumor suppressor in breast cancer progression." (PMID 35456486, 2022). "ARAP1-AS1 is overexpressed in breast cancer cells and ARAP1-AS1 silencing results in inhibited proliferation, blocked migration, and strengthened apoptosis of breast cancer cells via the microRNA-2110/histone deacetylase 2/perilipin 1 axis." (PMID 35291911, 2022). "AMPK (involved LIPE and LEP) and PPAR (involved PLIN1) were two significantly enriched pathways in luminal A breast cancer." (PMID 35692369, 2022). "For example, RNA-seq and microarray analysis revealed that PLIN1 can participate in breast cancer development, while patients with upregulated levels of PLIN1 mRNA present lower overall survival rates." (PMID 34067931, 2021). "LEP which inhibit apoptosis of breast cancer cells by coding leptin, while PLIN1 inhibits invasion, migration, and proliferation of cells." (PMID 34899291, 2021). "The expression level of PLIN1 is correlated with the prognosis of breast cancer patients and is expected to become a potential new gene therapy target for breast cancer." (PMID 33029112, 2020). "The reduced expression of PLIN1 is an independent predictor of OS in estrogen receptor–positive and luminal A-subtype breast cancer patients." (PMID 33194695, 2020). "Overexpression of PLIN1 can inhibit the proliferation, migration, and invasion of breast cancer cells." (PMID 33029112, 2020). "This seems to confirm the finding in an independent study using TCGA RNA-Seq data, where perilipin-1 (PLIN1) mRNA expression is found to be significantly downregulated in human breast cancers." (PMID 29268695, 2017). "We previously reported that PLIN1, a core component of lipid drops that regulates both triglyceride storage and lipolysis, is involved in breast cancer progression though PLIN1-mediated lipid metabolism." (PMID 29254166, 2017). "Exogenous overexpression of PLIN1 in breast cancer cell lines inhibited proliferation, migration, invasion as well as in vivo tumorigenesis in mice." (PMID 28412757, 2017).
breast carcinoma (continued). "Combining the results of gene ontology and protein interaction network analyses, we found PLIN1 exhibits significantly reduced expression in breast cancer samples compared with normal controls." (PMID 27359054, 2016). "We further performed a meta-analysis of the prognostic significance of PLIN1 expression in human breast cancer patients." (PMID 27359054, 2016). "Human breast cancer cell migration and invasion were further evaluated by the examining the effects of exogenous PLIN1." (PMID 27359054, 2016). "By meta-analysis of public microarray profiles, we confirmed the prognostic value of PLIN1 expression in breast cancer patients." (PMID 27359054, 2016). "We also demonstrated that the exogenous expression of PLIN1 in human breast cancer MCF-7 and MDA-MB-231 cells significantly inhibits cell proliferation, migration, invasion and in vivo tumorigenesis in mice." (PMID 27359054, 2016). "We first examined the effects of exogenous PLIN1 on the proliferation of the human breast cancer cell line MCF-7." (PMID 27359054, 2016). "We found that breast cancer patients with low PLIN1 mRNA had have significantly reduced overall survival (p = 0.03), which is consistent with our meta-analyses of the microarray datasets." (PMID 27359054, 2016). "To validate PLIN1 expression in breast cancer, we performed immunohistochemical analysis on a total of 40 pairs of human breast cancer tissues (10 pairs for each subtype)." (PMID 27359054, 2016). "ROC curves were generated and indicated that the PLIN1 mRNA levels in breast cancer samples differ significantly from those observed in control samples, with an AUC value of 0.93." (PMID 27359054, 2016). "Overall, we identify PLIN1 as a potential biomarker for multiple human cancer types, including breast cancer, low-grade glioma, hepatocellular carcinoma and sarcoma and highlight the prognostic value of PLIN1 mRNA levels in breast cancer outcomes." (PMID 27359054, 2016). "As PLIN1 exhibits significant prognostic significance in human breast cancers, we investigated the functional role of PLIN1 in breast cancer." (PMID 27359054, 2016). "Together, these data provide novel insights into a prognostic significance of PLIN1 in human breast cancer and reveal a potentially new gene therapy target for breast cancer." (PMID 27359054, 2016). "The expression levels of PLIN1 were further verified by immunohistochemical assessment in breast cancer tissues, and the resulting data were consistent with those from the RNA- sequencing and microarray assays." (PMID 27359054, 2016). "Using the cutoff value of 9.68, the sensitivity and specificity values of 0.55 and 0.96, respectively, were obtained, in the identification of patients with breast cancer, indicating that PLIN1 is indeed an excellent marker for human breast cancer." (PMID 27359054, 2016). "The expression of PLIN1 was significantly downregulated in 307 breast cancer samples from the TCGA database." (PMID 27359054, 2016). "Taken together, our data demonstrate that high PLIN1 levels significantly inhibit human breast cancer cell proliferation, invasion, migration, and in vivo tumorigenesis." (PMID 27359054, 2016). "We further investigated the correlation of PLIN1 mRNA levels with prognostic significance in human breast cancers by performing a meta-analysis using the Bc-GenExMiner v3.2 database." (PMID 27359054, 2016). "Here we found that perilipin-1 (PLIN1) mRNA expression is significantly downregulated in human breast cancer." (PMID 27359054, 2016). "Thus, ARAP1-AS1 exacerbates the development of breast cancer by inducing the transcriptional suppression of PLIN1 through the deacetylation activity of HDAC2 on the PLIN1 promoter." (PMID 39090630, 2024). "With no fine-tuning of our mammary tissue (GTEx) model, we see RNAPath is able to predict known marker genes, for example, PLIN1 in adipocytes (r score = 0.29, P-value = 2.27 × 10−19) or breast cancer related genes like AQP1 (r score = 0.32, P-value = 1.58 × 10−23)." (PMID 39003292, 2024).
breast carcinoma (continued). "Consistent with previous research on breast cancer, the present study demonstrated that PLIN1 expression was downregulated in GBM, that the expression level fell gradually with increasing WHO classification, and that low PLIN1 expression was related to an unfavorable outcome in patients with LGG." (PMID 37189627, 2023). "The study noted that PLIN1 plays a distinct role in regulating both triglyceride storage and lipolysis in adipocytes, and that reduced expression of PLIN1 could be an independent predictor of overall survival for breast cancer patients." (PMID 37609286, 2023). "In addition, we found that AMPK (involved LIPE and LEP) (p value = 0.003440464) and PPAR (involved PLIN1) (p value = 0.018732701) were two significantly enriched pathways in luminal A breast cancer." (PMID 35692369, 2022). "In addition, based on functional enrichment of DEmRNAs coexpressed with DElncRNAs, we found that AMPK (involved LIPE and LEP) and PPAR (involved PLIN1) were two significantly enriched pathways in luminal A breast cancer." (PMID 35692369, 2022). "In contrast, PLIN1 mRNA expression is significantly downregulated in human breast cancer." (PMID 33194695, 2020). "Alternatively, there could be another correlation between GPD1 and PLIN1 in the progression of breast cancer." (PMID 29254166, 2017). "Notably, the exogenous expression of PLIN1 in human breast cancer cell lines MCF-7 and MDA-MB-231 significantly inhibited cellular proliferation, migration and invasion." (PMID 27359054, 2016). "To determine whether PLIN1 is a potential prognostic biomarker for breast cancer, we assessed the mRNA levels of PLIN1 in human breast cancer tissues, as well as the role of PLIN1 in human breast cancers." (PMID 27359054, 2016). "However, further studies are needed to enhance our understanding of the mechanistic roles of PLIN1 in the development and progression of breast cancer." (PMID 27359054, 2016). "PLIN1 may affect tumor progression through PPARG/PPARγ pathway in breast cancer." (PMID 33029112, 2020). "Thus, the role of PLIN1 in human breast cancer warrants further investigations." (PMID 27359054, 2016). "Because estrogen receptor (ER) and nodal status in breast cancer are important prognostic indicators of recurrence and greatly influence treatment regimens, we next set out to identify the prognostic potential of PLIN1 expression in breast cancer patients with different ER and nodal statuses." (PMID 27359054, 2016). "The protein expression results of TUBB3, MCM2, MYOC, FN1, S100A7, and TFF1 were consistent with the mRNA expression result COL10A1, LEP, PLIN1, PGM5-AS1, and TRHDE-AD1 were capable of discriminating luminal A breast cancer and normal controls." (PMID 35692369, 2022). "COL10A1, LEP, PLIN1, PGM5-AS1, and TRHDE-AD1 were capable of discriminating luminal A breast cancer and normal controls." (PMID 35692369, 2022). "The results indicated that except for TFF1 (AUC = 0.774), COL10A1 (AUC = 1.000), LEP (AUC = 0.984), PLIN1 (AUC = 0.966), PGM5-AS1 (AUC = 0.969), and TRHDE-AD1 (AUC = 1.000) were capable of discriminating luminal A breast cancer and normal controls." (PMID 35692369, 2022). "In our study, PLIN1 was downregulated in our RNA sequencing and GSE65194 dataset and was capable of discriminating luminal A breast cancer and normal controls." (PMID 35692369, 2022). "Perilipin 1 (PLIN1) is expressed almost exclusively in adipose tissue, although there is a report of its expression in breast cancer." (PMID 28412757, 2017). "However, the effects of PLIN1 in breast cancer remain unknown." (PMID 27359054, 2016). "However, the role of PLIN1 in human cancer, particularly in human breast cancer, remains unknown." (PMID 27359054, 2016).
breast carcinoma (continued). "Because HER2 plays an important role in the development and progression of breast cancer by mediating multiple signals in cancer cells, our findings suggest that HER2 status is involved in the downregulation of PLIN1 mRNA expression." (PMID 27359054, 2016). "Finally, spots in the fourth cluster coexpress adipocyte markers (ADIPOQ, PLIN1, CIDEC) reflecting adipocyte-rich stroma that lead to microvasculature in breast cancer." (PMID 41249066, 2025). "PLIN1 expression has also been reported as a favorable marker of other types of cancer like breast cancer but not for SCLC." (PMID 33807668, 2021). "Therefore, the study suggested that AC245452.1 may be involved in the occurrence of luminal A breast cancer by regulating the GPD1 and PLIN1." (PMID 35692369, 2022). "Critically, we observed no obvious influence of adipocytic TAZ knockdown on adipocyte differentiation measured by Oil-Red O staining and perilipin 1 expression or breast cancer cell toxicity in the CM system measured by CCK assay, ruling out the effects of adipogenesis and breast cancer apoptosis." (PMID 33318171, 2020).
lipodystrophy (24 papers, 2012 to 2025). A congenital or acquired disorder characterized by abnormal loss or redistribution of the adipose tissue in the body. "PLIN1 has been suggested as a useful diagnostic marker for lipodystrophy, a disease characterized by an inability to produce or maintain healthy adipose tissue in the body." (PMID 37998612, 2023). "Rare PLIN1 frameshift variants that extend the translated protein have been described to cause lipodystrophy." (PMID 35235652, 2022). "This provides a unique opportunity to test the effect of PLIN1 variants on lipodystrophy phenotypes in a population-based setting." (PMID 35235652, 2022). "Consistently, PLIN1-KO mice and humans with frameshift mutations altering the C-terminus of PLIN1 show unrestricted basal lipolysis and suffer from lipodystrophy." (PMID 32290093, 2020). "We performed histological and molecular studies for patients referred to our French National Reference Center for Rare Diseases of Insulin Secretion and Insulin Sensitivity for lipodystrophy and/or insulin resistance and carrying PLIN1 frameshift variants." (PMID 31504636, 2019). "We used the type 2 diabetes knowledge portal to assess the association of PLIN1 to the biomarkers of lipodystrophy." (PMID 30020498, 2018). "We also investigated the frequency of PLIN1 null variants in 138,632 people in gnomAD and lipodystrophy and diabetes phenotypes in 17,000 individuals in the diabetes knowledge portal." (PMID 30020498, 2018). "Only three specific PLIN1 variants have been reported to cause lipodystrophy; our aim was to investigate if null variants in the gene were associated with the same phenotype." (PMID 30020498, 2018). "PLIN1 is currently screened on diagnostic targeted gene panel tests for lipodystrophy, insulin resistance, and diabetes." (PMID 30020498, 2018). "As part of a routine gene panel test for genes reported to be causative of lipodystrophy and monogenic diabetes, we sequenced PLIN1 in 1323 patients referred for Maturity Onset Diabetes of the Young (MODY) testing." (PMID 30020498, 2018). "Doubt over haploinsufficiency in PLIN1 causing lipodystrophy has important consequences for genetic testing." (PMID 30020498, 2018). "Plin1 deficiency (Plin1-/-) in mice results in low body fat and aberrant lipolysis, and Plin1 mutations in human cause partial lipodystrophy associated with hyperlipidemia and insulin resistance." (PMID 25695774, 2015). "The role of perilipin (PLIN1—a protein almost exclusively found in adipocytes) in lipodystrophy was first suggested in 2011 by the identification of deleterious genetic variants in PLIN1 in familial forms of lipodystrophy." (PMID 39785092, 2025). "This work aimed to test whether PLIN1 protein-truncating variants (PTVs) cause lipodystrophy in a large population-based cohort." (PMID 35235652, 2022). "PLIN1 has already been associated with intramuscular fat in pigs and lipodystrophy in humans." (PMID 34381378, 2021). "PLIN1 frameshift variants were reported to cause lipodystrophy." (PMID 30020498, 2018). "We investigated if null variants in PLIN1 cause lipodystrophy." (PMID 30020498, 2018). "Loss of Plin1 impaired the differentiation and development of adipose cells, which might be one of the pathological bases for lipodystrophy in patients with Plin1 mutation." (PMID 25695774, 2015). "This suggests that the lipodystrophy phenotype observed in FPLD type 4 might be due to a peculiar alteration in PLIN1 function caused by those specific C-terminal frameshift variants and not a simple heterozygous loss of PLIN1 function (i.e. haploinsufficiency)." (PMID 35999217, 2022). "PLIN1 studies have so far been based on a small number of clinically ascertained individuals, so there is still a question as to the role of PLIN1 PTVs in lipodystrophy." (PMID 35235652, 2022). "In humans, heterozygous mutations of PLIN1 lead to lipodystrophy, hypercholesterolemia and FLD, most probably via impaired perilipin 1-driven lipolysis in adipose tissue." (PMID 36611868, 2022).